CASP1 (caspase 1)
Diseases named in the same sentence as CASP1 in open-access papers (continued):
Sharing a sentence is not in itself a finding about the gene and the disease.
atherosclerosis (continued). "These issues spur us to test the role and mechanism for caspase 1 inhibition in regulating vascular inflammation and atherosclerosis." (PMID 35641492, 2022). "Together, these studies suggest that modulation of NLRP3- and caspase 1-mediated pyroptosis offers significant health benefits for patients with advanced atherosclerosis." (PMID 35625908, 2022). "Caspase-1-dependent pyroptotic cell death of ECs and resulting increased inflammatory response are involved in atherosclerosis, especially in early atherosclerotic vascular injury." (PMID 35096837, 2021). "Consistent with the knockout of AIM2, knockout of Caspase-1/11 or GSDMD alleviated atherosclerosis in mice Aim2 knockout in Jak2V617Fmice." (PMID 34122076, 2021). "In ApoE-deficient mice dapagliflozin inhibited interleukin-1β secretion by macrophages and reduced atherosclerosis via the ROS-NLRP3-caspase-1 pathway." (PMID 34131781, 2021). "It has also been shown that TREM-1 apparently mediates ox-LDL-induced endothelial cell pyroptosis, a cell death process found in atherosclerosis, which is dependent on caspase-1 activation and IL-1β and IL-18 production." (PMID 33814983, 2021). "Tumor spleen Treg and tumor Treg shared one upregulated caspase-1 secretomic pathway, fluid shear stress and atherosclerosis." (PMID 34084175, 2021). "Another study employing a caspase-1 knockout in a high-fat diet animal model showed a significant reduction in the formation of atherosclerosis plaques." (PMID 32378144, 2021). "A study of nicotine exacerbating atherosclerosis showed that increased intracellular ROS caused macrophages pyroptosis, which is manifested by the assembly of NLRP3 inflammasome, the cleavage of caspase-1 and the increase of IL-1β, IL-18, and GSDMD production." (PMID 34122076, 2021). "It has been reported that the inflammasome Nlrp3-caspase-1-IL-1β pathway triggers vascular endothelial inflammation in the progression of atherosclerosis." (PMID 31993073, 2020). "The NLRP3 inflammasome, an innate immune-signaling complex, regulates CASP1 activation and the subsequent processing of pro-IL-1β, triggers vascular wall inflammatory responses and leads to the progression of atherosclerosis." (PMID 32054994, 2020). "Cholesterol crystals induce Nrf2-related signaling pathways, including the caspase-1-independent IL-1 signaling and NLRP3/caspase-1-dependent IL-1 pathways, leading to atherosclerosis." (PMID 31354731, 2019). "Because both NLRP3 and caspase-1 deficiency decreases atherosclerosis in ApoE-/- mice, therapeutic modulation of NLRP3 or caspase-1 activity is likely to offer significant health benefits for patients with severe atherosclerosis." (PMID 31019462, 2019). "In addition, by using a murine model of atherosclerosis, it was shown that myeloid Abca1/g1 deficiency enhanced caspase-1 activation in monocytes, macrophages, and neutrophils, resulting in enhanced atherogenesis that was suppressed by Nlrp3 or Caspase-1/11 deficiency." (PMID 31374929, 2019). "After analyzing NLRP3−/−, ASC−/−, or caspase-1−/− on Apoe-null mice fed with a high-fat diet for 11 weeks, the team observed no significant change in cell infiltration, plaque stability, and atherosclerosis progression." (PMID 29850631, 2018). "The rationale to focus on the caspase-1 function in the aorta was because our recent reports showed that caspase-1 promotes vascular inflammation and atherosclerosis in the aorta." (PMID 28153032, 2017). "ApoE/caspase-1 double knockout models demonstrate a slower progression of atherosclerosis." (PMID 39936975, 2025). "Recent research demonstrated VX-765 ameliorates vascular inflammation and atherosclerosis in a murine model of atherosclerosis, suggesting another potential therapeutic benefit of caspase-1 inhibition for SLE patients, as cardiovascular events are a significant cause of death in this population." (PMID 41436137, 2025).
atherosclerosis (continued). "ZL, in combination with atorvastatin, can inhibit the activation of the NF-κB/NLRP3 signaling pathway and limit the release of p-NF-κB, NLRP3, caspase-1, IL-1β, and IL-18, thereby alleviating vascular inflammation and significantly attenuating atherosclerosis in rabbits." (PMID 40373162, 2025). "We proposed that the NETs, ASC, Caspase-1, IL-1β pathway is an important regulator of post-stroke inflammation which might exacerbate atherosclerosis." (PMID 39737165, 2024). "Moreover, the NLRP3 inflammasome, a complex comprising the NLRP3 receptor, ASC adapter, and pro-caspase-1, plays a pivotal role in atherosclerosis development by catalyzing the maturation of caspase-1, which in turn generates IL-1β/IL-18 from pro-IL-1β/IL-18." (PMID 38919547, 2024). "Additionally, the non-canonical NF-κB pathway triggers NLRP3-inflammasome-mediated endothelial pyroptosis and atherosclerosis via activating caspase-1 and GSDM-D in human aortic endothelial cells." (PMID 39770410, 2024). "While mice with EC-restricted KO of pyroptosis machinery have not been generated to study atherosclerosis, mechanistic insights can still be gained using mouse models with global deficiency of caspase-1 or NLRP-3." (PMID 37894840, 2023). "To determine the causative effect of caspase-1 in HIV-1-associated atherosclerosis, we compared the development of atherosclerosis in caspase-1-sufficient vs. -deficient mice carrying the HIV transgene with an atherogenic background (Tg26+/−/ApoE−/−/Casp-1+/+ vs. Tg26+/−/ApoE−/−/Casp-1−/−)." (PMID 37629052, 2023). "The NLRP3 inflammasome activates caspase-1, acts on the precursor molecules of IL-1β and IL-18, and promotes the maturation and secretion of IL-1β and IL-18 to trigger an inflammatory response and further aggravate atherosclerosis." (PMID 37679676, 2023). "We found that the deficiency in caspase-1 in Tg26+/−/ApoE−/−/Casp-1−/− mice resulted in significantly fewer atherosclerosis plaques in the thoracic aorta, but not in the entire aorta including the arch, thoracic, and abdominal aorta, nor in the aortic root." (PMID 37629052, 2023). "However, SET7 siRNA in atherosclerosis downregulated 57 canonical SGs, 10 caspase 1 SGs, 12 caspase 4 SGs, 81 exosomes SGs, one WBP SG, and two autophagy SGs." (PMID 35320939, 2022). "Undoubtedly, our work significantly extends previous findings about caspase 1 in atherosclerosis." (PMID 35641492, 2022). "Considering that inflammasome and caspase-1 are important factors that induce pyroptosis, both the absence of inflammasome and caspase-1 deficiency alleviate atherosclerosis." (PMID 35096837, 2021). "As one of the most important multimeric protein complexes, NLRP3 inflammasome activation leads to increased cleavage of caspase-1 and downstream IL-1β production, and plays a pathological role in many diseases including diabetes, atherosclerosis and cardiovascular diseases." (PMID 34583676, 2021). "Subsequently, active caspase-1 leads to proteolytic cleavage of pro-inflammatory cytokines such as pro-IL-1β and pro-IL-18 into their mature and active forms, which are the most important cytokines involved in the progression of atherosclerosis." (PMID 32378144, 2021). "In the context of dyslipidemia and inflammation, the caspase-1–inflammasome pathway in ECs can sense the elevated lipids or DAMPs and other inflammatory mediators and activate ECs, which is the foremost step in the progress of atherosclerosis." (PMID 35096837, 2021). "Caspase-1 deficiency reduces endothelial cell activation and infiltration of monocytes into intima and attenuates ox-LDL-induced VSMC pyroptosis and IL-1β processing, which all suppress the development of atherosclerosis." (PMID 35096837, 2021).
atherosclerosis (continued). "For example, caspase-11–mediated endothelial pyroptosis is requisite for endotoxemia-induced lung injury, while endothelial cell pyroptosis via caspase-1–dependent inflammasome activation leads to endothelial dysfunction in hyperhomocysteinemia-related vascular inflammation and atherosclerosis." (PMID 30718392, 2019). "The NLRP3 inflammasome, a multiprotein complex including NLRP3, caspase-1, IL-1β and ASC, has been widely shown to be an essential step in cardiovascular disease and is linked to atrial fibrillation, atherosclerosis, diabetic cardiomyopathy and cardiac remodeling." (PMID 31354519, 2019). "However, the direct effects of exercise on ER stress-mediated endothelial dysfunction and on ER stress-associated caspase-1 and UCP-2 signaling in atherosclerosis merit further examination." (PMID 29784903, 2018). "The importance of NLRP3/caspase-1 in atherosclerosis has been questioned." (PMID 24686534, 2014). "Furthermore, the finding that febuxostat can inhibit the production of caspase-1-dependent and -independent cytokine/chemokine makes it an attractive therapeutic agent in atherosclerosis." (PMID 24686534, 2014). "The robustness of this pathway is normally well-controlled by NLR stringency; however, “hair-trigger” activation of caspase-1 drives inflammation during atherosclerosis, diabetes, Alzheimer's, inflammatory bowel disease, cancer, and several auto-inflammatory genetic disorders." (PMID 24367258, 2013). "In addition, loss of caspase-1 activity which involves the inflammatory process in human atherosclerotic vessel has shown to reduce atherosclerosis lesion formation in Casp1-/- Apo E-/- mice." (PMID 22520940, 2012). "Deficiency of each of the three inflammasome proteins (NLRP3, ASC, Caspase 1) has been shown to reduce atherosclerotic lesion or plaque size, and the inflammasome regulates the production and recruitment of monocytes through IL-1β in the early stages of atherosclerosis." (PMID 40956333, 2025). "Moreover, VX-765 has demonstrated inhibition of the harmful death of vascular smooth muscle cells (VSMCs) in atherosclerosis, indicating that targeting caspase-1 activity could be a promising therapeutic approach for atherosclerotic cardiovascular diseases." (PMID 38475920, 2024). "NLRP3, caspase-1, and apoptosis associated speck-like protein (ASC) are the key components of the NLRP3 inflammasome, which have been found to be highly expressed in plaques of the aorta and carotid arteries, as well as the subcutaneous fat of patients with atherosclerosis." (PMID 36082127, 2022). "Also, the mechanism that caspase 1 inhibition/deletion mitigates atherosclerosis is unclear." (PMID 35641492, 2022). "Similarly, silencing IL-1α, IL-1β, and caspase-1 respectively in Apoe−/− mice could attenuate atherosclerosis development." (PMID 29850631, 2018). "ASC and caspase-1, as key adaptor proteins of the NLRP3 inflammasome, exhibit sharply increased levels during the progression of atherosclerosis." (PMID 39936975, 2025). "Among the most widely studied in the context of atherosclerosis is the cytosolic multiprotein signaling complex called the NLRP3 inflammasome, which serves as a platform for the activation of caspase-1 and promotes the synthesis of pro-inflammatory cytokines." (PMID 39055657, 2024). "We used IHC to preliminarily detect the expression of GSDMD, CASP1, NLRC4, AIM2 and IL18 in advanced atherosclerosis plaques of patients." (PMID 38167983, 2024). "We identified a set of genes (GSDMD, CASP1, NLRC4, AIM2, and IL18) closely related to atherosclerosis, particularly in atherosclerotic lesions with high pyroptosis scores." (PMID 38167983, 2024). "The ratios of upregulation versus downregulation of canonical secretome, caspase 1 secretome, caspase 4 secretome, exosome secretome, WPB secretome and autophagy secretome in atherosclerosis, CKD, and AAA were high in atherosclerosis and CKD." (PMID 35320939, 2022).
atherosclerosis (continued). "The vital role of pyroptosis in the pathogenesis of atherosclerosis has generated a few specific inhibitors or agents that target bioactive substances such as NLRP3, caspase-1, caspase-4/5/11, GSDMD, and other candidates in relation to pyroptosis pathway." (PMID 36304814, 2022). "Molecular mechanism of nicotine-induced atherosclerosis is when nicotine enters the endothelial cell and increase production of ROS which activates NLRP3 inflammasome that leads to the activation of caspase-1." (PMID 36093338, 2022). "The modulation patterns of canonical and exosome secretomes in atherosclerosis, CKD and AAA were similar; and the modulation scales of caspase 4 secretome were bigger than that of caspase 1 secretome in these four diseases." (PMID 35320939, 2022). "Coronavirus disease-COVID-19 and lipid and atherosclerosis connect with TRAF3, TLR2, SELP and CASP1 deregulated molecules." (PMID 36553678, 2022). "The severity of atherosclerosis correlates with inflammasome activity and NLRP3/caspase 1-mediated generation of IL-1β and IL-1α in human atherosclerotic plaque." (PMID 33172487, 2020). "We conclude that ER stress plays a significant role in endothelial dysfunction of resistance arteries in atherosclerosis and that exercise attenuates ER stress and regulates its critical downstream signaling pathways including eNOS, UCP-2 and caspase-1." (PMID 29784903, 2018). "A limitation of the current study is the absence of cellular and molecular expressions data of ER stress markers and key factors such as caspase-1, UCP-2, and eNOS affected by atherosclerosis and exercise training." (PMID 29784903, 2018). "For one thing, CHC can enhance vascular wall inflammatory responses and lead to atherosclerosis by active NLRP3 inflammasomes, which regulate caspase-1 activation and subsequent processing of pro-IL-1β, triggering IL-1 secretion." (PMID 29133791, 2017). "Interestingly, ZL effectively alleviates vascular endothelial cells in atherosclerosis by regulating the miR-30b-5p/NLRP3 axis and significantly reduces the AS-related mRNA expression levels of NLRP3, ASC, Caspase 1, IL-1 β, and IL-18." (PMID 40373162, 2025). "Finally, VX765, a caspase-1 inhibitor prodrug activated by intracellular esterases, attenuated VSMC pyroptosis and atherosclerosis progression in ApoE−/− mice on a Western diet." (PMID 36555579, 2022). "We found that VSMCs (Myh11+) undergoing transdifferentiation to macrophages-like cells in human atherosclerotic plaques co-express cleaved caspase 1 as well as IL-1β, indicating the involvement of NLRP3 inflammasome activation in VSMCs phenotypic switch in human atherosclerosis." (PMID 35008765, 2021). "Recently, absent in melanoma 2 (AIM2) inflammasome, caspase 1 and 11, and GsdmD were shown to play in role in clonal hematopoiesis mediated exacerbation of atherosclerosis." (PMID 34395445, 2021). "Further studies in similar mouse models as well showed decreased severity of atherosclerosis in mice lacking NLRP3, caspase-1 or IL-1β, while in another study NLRP3 inflammasomes were not critically implicated in atherosclerosis progression." (PMID 31795299, 2019). "Dapagliflozin may be of therapeutic potential for diabetic atherosclerosis induced by high-fat diet, and these benefits may depend on the inhibitory effect on the secretion of IL-1β by macrophages via the ROS-NLRP3-caspase-1 pathway." (PMID 28104929, 2016). "Although the role of these factors in atherosclerosis needs to be verified by further in vivo work, these discoveries have one thing in common that atherosclerosis-related ECs pyroptosis is achieved through the assembly of NLRP3 inflammasome and the activation of caspase-1." (PMID 34122076, 2021).
atherosclerosis (continued). "Moreover, dapagliflozin inhibited the expression of NLRP3, ASC, caspase-1, IL-1β, and IL-18 in DM mice, and such expression was also decreased in the nondiabetic atherosclerosis model (not statistically significant)." (PMID 28104929, 2016). "Thus, the inhibition of caspase-1, NLRP3, or GSDMD in dyslipidemic and inflammatory contexts prevents endothelial pyroptosis and improves endothelial survival, thereby preserving vascular intima integrity, reducing vascular inflammation, and further attenuating the progression of atherosclerosis." (PMID 37894840, 2023).